JAK2 (Janus kinase 2)
Diseases named in the same sentence as JAK2 in open-access papers (continued):
Sharing a sentence is not in itself a finding about the gene and the disease.
myelofibrosis (continued). "Ruxolitinib (RUX), an oral JAK inhibitor approved by the FDA for the treatment of myelofibrosis, polycythemia vera, and graft versus host disease works through reducing the abundance of cytokines and growth factor receptors that utilize JAK1 and JAK2." (PMID 38319731, 2024). "Gangat, N., Begna, K.H., Al-Kali, A. Hogan, W, Litzow, M, Pardanani, A, Tefferi, A. Determinants of survival and retrospective comparisons of 183 clinical trial patients with myelofibrosis treated with momelotinib, ruxolitinib, fedratinib or BMS- 911543 JAK2 inhibitor." (PMID 39400853, 2024). "Triple-negative myelofibrosis (TN MF) is diagnosed in the absence of JAK2, MPL, and CALR mutations while otherwise meeting morphologic and laboratory criteria for myelofibrosis." (PMID 37760623, 2023). "We present a case of a 37-year-old male initially diagnosed with myelofibrosis based on a history of pancytopenia, warm submandibular and submental swelling, and negative BCR-ABL and JAK2 mutations." (PMID 38149134, 2023). "Results were most notable for an activating mutation in the MPL (W515L) transmembrane domain in 4/45 (9%) patients with JAK2-negative myelofibrosis." (PMID 37760623, 2023). "In a study of two mouse models of thrombopoietin and constitutively active JAK2 mutant (JAKV617F)-induced myelofibrosis, HSP27 was found to regulate the proliferation of JAK2V617F-positive cells and interact directly with JAK2/STAT5 to protect STAT5 from dephosphorylation." (PMID 37252119, 2023). "However, JAK1 and JAK2, which are upstream of STAT3, have been mainly demonstrated to play a role in blood system diseases such as myelofibrosis and lymphoma." (PMID 35382859, 2022). "Some patients with myelofibrosis do not have splenomegaly or significant symptom burden, instead, featuring problematic cytopenias that are likely to be exacerbated by JAK2 inhibitors." (PMID 35082276, 2022). "The JAK2 inhibitor fedratinib has been used to treat patients with myelofibrosis, with responses observed for both JAK2 V617F-positive and -negative patients, including patients resistant to ruxolitinib." (PMID 36551764, 2022). "Between different JAK/STAT isoforms, JAK2/STAT3 appears to be predominant for the cellular changes observed in ILDs and it is involved also in other diseases with a fibrotic phenotype (such as myelofibrosis, liver, myocardial, kidney, and skin fibrosis)." (PMID 36556466, 2022). "Currently, the ongoing phase III TRANSFORM-1 trial is evaluating the combination of Navitoclax and ruxolitinib vs placebo and ruxolitinib in adults with primary or secondary myelofibrosis who have not received JAK2 inhibitors." (PMID 34667663, 2021). "Ruxolitinib is a selective JAK1 and JAK2 inhibitor that targets JAK/STAT-associated signaling, exhibiting an effective clinical treatment of myelofibrosis adopted by FDA, which was used to confirm the effect of ENC1 on activation of the JAK2/STAT5/AKT axis in CRC cells." (PMID 33816464, 2021). "Fedratinib (TG101348) is a JAK2-selective inhibitor which demonstrated clinical benefits in patients with MF in early-phase clinical trials, and is approved by the Food and Drug Administration (FDA) as the first drug to treat myelofibrosis." (PMID 33686952, 2021). "The study of PV patients found that the age of onset in the JAK2-V617F-positive group was higher than that in the negative group, which was clinically more prone to complications of myelofibrosis, hemorrhage and thrombosis." (PMID 32095159, 2020). "The development of JAK2 V617F inhibitor, ruxolitinib as the treatment for those with JAK2 V617F myelofibrosis has not been as successful as those CML with TKI." (PMID 30564475, 2018). "We determined whether the approved myelofibrosis drug ruxolitinib (Jakafi®), an inhibitor of Janus kinases 1/2 (JAK1 and JAK2), could be repurposed as an anti-cancer agent for solid tumors." (PMID 27379204, 2016).
myelofibrosis (continued). "Another study reported the case of a JAK-2 mutation-negative and MPL W515 mutation-positive patient exhibiting grade 2 myelofibrosis; however, no details regarding clinical course, laboratory results or bone marrow biopys results were provided." (PMID 25621045, 2015). "On the other hand, a substantial stability was observed in 88% (22/25) of patients with myelofibrosis while the increase in JAK2 expression in three of 44 patients (6.8%) did not correspond to disease progression." (PMID 25584101, 2015). "Therefore, we decided to compare in mice the effect of a JAK2 inhibitor, Fedratinib, in MPN models of increasing severity: polycythemia vera (PV), post-PV myelofibrosis (PPMF) and rapid post-essential thrombocythemia MF (PTMF)." (PMID 26176817, 2015). "Recent clinical trials with JAK2 inhibitors showed significant improvements in splenomegaly and constitutional symptoms in patients with myelofibrosis but meaningful molecular responses were not documented." (PMID 23382981, 2013). "TG-101348 (Fedratinib), a selective JAK2 inhibitor approved for myelofibrosis, has not yet been tested in sepsis but may exert therapeutic effects by modulating the JAK2/STAT1 signaling axis, a key regulator of inflammation and immune dysregulation in sepsis." (PMID 40792069, 2025). "Moreover, FERM‐JAK2 transplanted mice showed grade II myelofibrosis already 60 days after transplantation, whereas JAK2‐V617F transplanted mice did not display any signs of myelofibrosis at that stage." (PMID 38104968, 2024). "The pathogenesis of primary myelofibrosis is not determined solely by alterations in JAK2, CALR, and MPL and likely involves a much broader landscape of somatic mutations, which themselves affect both clinical features of disease and overall survival in various capacities." (PMID 37760623, 2023). "Additionally, non-canonical JAK2 and MPL mutations have been reported in myelofibrosis and are not limited to triple negative MPN." (PMID 36810551, 2023). "The combination of JAK2 and ERK inhibition is being tested in a clinical trial (NCT04097821) for myelofibrosis and perhaps combinations of MEK inhibition with BCL-2 inhibition, as well as combinations involving BET or PI3Kdelta inhibitors, could be effective therapeutic strategies in MPN." (PMID 35082276, 2022). "The JAK2 assay result was also negative, considering the possibility of myelofibrosis." (PMID 36482523, 2022). "With a negative breakpoint cluster region protein‐abelson murine leukaemia viral oncogene homolog 1 (BCR‐ABL1) on peripheral blood fluorescence in situ hybridization, a presumptive diagnosis of primary myelofibrosis awaited the results of a janus kinase 2 (JAK2) status which was negative." (PMID 35845189, 2021). "In vitro studies showed that the combination of JAK2 and BET inhibition resulted in enhanced cell apoptosis and the growth arrest of blastic cells from post-MPN AML, while in preclinical animal models of myelofibrosis it was able to reduce fibrosis and prolong survival." (PMID 34680226, 2021). "Despite conditions of systemic inflammation, the chronic proliferation of JAK2 V617F-positive PV is sustained over decades with relatively low cumulative incidence of blast transformation (to AML) and fibrotic progression to post-PV myelofibrosis (post-PV MF,)." (PMID 32272770, 2020). "However, a recent study reported a 20‐fold increase (0.3%‐5.8%) in the prevalence of aggressive B‐cell lymphomas in myelofibrosis patients treated with vs without JAK2 inhibitors." (PMID 30874354, 2019). "How HSP27 impacts myelofibrosis development is not yet understood, but it may involve the JAK2/STAT5 signalling pathway." (PMID 29650953, 2018). "We determined whether the myelofibrosis drug ruxolitinib, an inhibitor of Janus kinases 1/2 (JAK1 and JAK2), could interact with the multiple sclerosis drug dimethyl-fumarate (DMF) to kill tumor cells; studies used the in vivo active form of the drug, mono-methyl fumarate (MMF)." (PMID 26981780, 2016).
myelofibrosis (continued). "This sets up a vicious cycle in which the poor negative response inhibition of the JAK2 mutation clone by inflammatory cytokine TNF-α produces more ROS, inducing more genetic alteration changes that eventually lead to the development of myelofibrosis or leukemia, as proposed by Hasselbalch." (PMID 39157201, 2024). "The additional JAK2 V617F somatic variant carriers in our database who did not have a TAA were between 58- to 83-years-old, and clinical features included muscle pain and weakness, venous thrombosis, myelofibrosis, polycythemia vera, stroke, cardiomyopathy, and prostate cancer." (PMID 39062663, 2024). "Interestingly, in the Controlled Myelofibrosis Study with Oral JAK Inhibitor Treatment (COMFORT)-1 and COMFORT-2 studies, it was observed that the benefits of ruxolitinib were independent of the presence of the JAK2 mutation." (PMID 35145818, 2022). "However, the survival rate of myelofibrosis patients treated with INCB018424 is not different from patients treated with standard therapy and it is still ambiguous if the Jak2V617F allele burden is effectively improved upon Jak2 inhibitor treatment." (PMID 23301855, 2013). "Additionally, we included all-cause death as part of our outcome of interest, and, therefore, the contribution of JAK2 mutation and WBC on CV-specific death is unclear, given that these variables are also risk factors for non-CV death, including transformation to acute leukemia or myelofibrosis." (PMID 37367089, 2023). "Fortunately, most of the CHIP-derived mutant/variant genes are not currently actionable for solid tumour, although a JAK2 inhibitor (fedratinib) has been approved by the US FDA for the treatment of the rare bone marrow disease, myelofibrosis." (PMID 35055414, 2022).
polycythemia vera (336 papers, 2006 to 2026). "The JAK2 V617F mutation was most prevalent in essential thrombocythemia (53.2%) and polycythemia vera (41.2%)." (PMID 41825406, 2026). "The patient exhibited an unprecedented 80% allele frequency of JAK2 V617F, significantly exceeding the average 30 to 50% observed in typical polycythemia vera cases, which led to abnormal enhancement of thrombopoietin signaling and megakaryocyte proliferation." (PMID 41560006, 2026). "Subsequent work-up confirmed polycythemia vera based on the presence of a JAK2 V617F mutation and suppressed erythropoietin levels." (PMID 41893451, 2026). "A classic example is the JAK2 V617F mutation, found in over 90% of patients with polycythemia vera and in a significant proportion of those with essential thrombocythemia or primary myelofibrosis." (PMID 41438753, 2025). "JAK2 mutations are common in MPNs, such as polycythemia vera (PV) (approximately 90%–95%), essential thrombocytopenia (ET) (60%), and primary myelofibrosis (PMF) (approximately 57%)." (PMID 39744945, 2025). "Activating mutations in JAK2 are present in 98% of patients with polycythemia vera, but molecular genetic testing is relatively costly and is not universally available across clinical laboratories." (PMID 40806795, 2025). "JAK-2 mutations, clinically manifesting as polycythemia vera, essential thrombocythemia, or primary myelofibrosis, carry an increased thrombotic risk, potentially leading to ACS and coronary ischemia." (PMID 40310443, 2025). "Specific mutations in Janus kinase 2 gene have been found to increase the risk of developing polycythemia vera, according to studies that investigated the genetic component of the disease." (PMID 40587754, 2025). "In five out of 21 patients, coagulopathies (JAK2-mutation, polycythemia vera, thalassemia, antiphospholipid syndrome) were detected as the reason for PVT." (PMID 39860069, 2025). "Polycythemia vera is a chronic myeloproliferative disorder characterized by a somatic mutation affecting JAK2 cytokine receptors that leads to the abnormal proliferation of myeloid hematopoietic cells." (PMID 40123933, 2025). "For example, JAK2 as a primary mutation often leads to polycythemia vera (PV), whereas, as a secondary event, it commonly results in essential thrombocythemia (ET)." (PMID 40140631, 2025). "Polycythemia vera had been diagnosed six years earlier based on erythrocytosis (hematocrit ~70%), the presence of the JAK2 V617F mutation, and low serum erythropoietin levels (2.1 mIU/mL; normal range: 4-24 mIU/mL)." (PMID 40271338, 2025). "Polycythemia vera (PV) is characterized by clonal hematopoietic stem or progenitor cells with constitutively active somatic mutation(s) in the Janus kinase 2 gene." (PMID 39804351, 2025). "The most well-known cause of primary polycythemia is polycythemia vera (PV), typically caused by a mutation in the JAK2 gene, which leads to increased signaling of the JAK-STAT pathway and clonal proliferation of erythrocyte precursors." (PMID 40248540, 2025). "The serum EPO level was elevated, and a bone marrow biopsy returned positive for JAK-2 mutation indicating the diagnosis of polycythemia vera despite the high EPO level." (PMID 39421127, 2024). "Ruxolitinib, a JAK1/JAK2 inhibitor, has shown clinical benefits in polycythemia vera (PV) patients which carry an activity mutation of JAK2 gene (i.e., V617F)." (PMID 39188724, 2024). "A JAK2 V617F variant with a VAF of 20% was identified around the time of her diagnosis with polycythemia vera." (PMID 39062663, 2024). "Polycythemia vera, the commonest primary erythrocytosis, results from pathogenic variants in JAK2 in ∼98% of cases." (PMID 37428608, 2023). "Polycythemia vera (PV) is a chronic myeloproliferative neoplasm characterized by erythrocytosis and driven, in almost all cases, by mutations in the JAK2 gene." (PMID 37509564, 2023). "We detected different risk factors (polycythemia vera-PV with JAK2 V617F mutation and inherited low-risk thrombophilia)." (PMID 37240720, 2023).
polycythemia vera (continued). "The JAK2 protein is important for controlling the production of blood cells from hematopoietic stem cells and gain-of-function mutations have been linked to polycythemia vera and idiopathic erythrocytosis." (PMID 36890172, 2023). "Particularly, patients #14 and #24 carry the JAK2 c.1849G > T; p.Val617Phe variant, associated with polycythaemia vera, essential thrombocythaemia and primary myelofibrosis." (PMID 36550207, 2023). "Mutations in JAK2 Exon 12 have also been identified in MPNs but are more common in polycythemia vera." (PMID 37760623, 2023). "These red cell diseases can be the result of multiple genetic causes; the main one being the acquired V617F mutation in the JAK2 gene [present in more than 95% of Polycythemia Vera (PV) cases] causing constitutive activation of the JAK2 kinase in cell lines." (PMID 37239426, 2023). "MPNs including polycythemia vera (PV), essential thrombocythemia (ET), and MF are characterized by overactive Jak/Stat pathway signaling, usually resulting from mutations in JAK2, MPL, or CALR." (PMID 37760623, 2023). "The most notable JH2 domain genetic alterations include JAK1 V658F and the homologous JAK2 V617F mutation known to cause Polycythemia vera (PV)." (PMID 37834019, 2023). "Polycythemia vera (PV) is a hematopoietic stem cell (HSC) neoplasm driven by somatic JAK2 mutations, characterized by the overproduction of red blood cells (RBCs) uncoupled from mechanisms that regulate erythropoiesis." (PMID 37095207, 2023). "In contrast, the most frequent form of primary erythrocytosis is the myeloproliferative neoplasm of polycythemia vera (PV) that is characterised by the presence of the JAK2 V617F somatic mutation in approximately 98% of cases." (PMID 36299528, 2022). "By applying RNA‐sequencing on granulocytes of 113 MPN patients, we demonstrate that PD‐L1 expression is highest among polycythemia vera patients and that PD‐L1 expression correlates with JAK2‐V617F mutational burden (R = 0.52; p < .0001)." (PMID 35015307, 2022). "In people with polycythemia vera, the JAK2 gene is overactive because of the underlying genetic change." (PMID 35456443, 2022). "In humans, analysis of the TET2 gene in bone marrow cells from 320 patients with myeloid cancers identified TET2 defects in 13 patients with polycythemia vera, all of whom also displayed the JAK2 V617F mutation." (PMID 35456443, 2022). "The chronic myeloproliferative neoplasms (MPNs), including essential thrombocythemia (ET), polycythemia vera (PV) and myelofibrosis (MF), are frequently characterized by the JAK2 mutations." (PMID 35741115, 2022). "On the other hand, the JAK V617F (somatic mutation of JAK2) parameter from this group should be investigated as it is a clear exclusion or confirmation of polycythemia vera as the primary disease." (PMID 35453637, 2022). "Primary erythrocytosis, also known as polycythemia vera (PV) is described as the outcome of alterations in the bone marrow that are typically acquired by JAK2 somatic mutations." (PMID 35304527, 2022). "In this case, a 51-year-old woman was diagnosed with polycythemia vera and concomitant JAK2/V617F mutations in July 2019." (PMID 35960050, 2022). "Specifically, the JAK2 V617F mutation is instrumental in differentiating polycythemia vera from secondary erythrocytosis." (PMID 35215273, 2022). "Virtually all patients with Polycythemia vera (PV), harbor a JAK2 mutation, and 14–20% of individuals with carry a karyotype abnormality." (PMID 34804065, 2021). "A discrepancy has been reported regarding the JAK2 V617F mutation in patients with essential thrombocythemia and polycythemia vera, and also regarding the type A mutation of NPM1 in acute myeloid leukemia (AML)." (PMID 33806359, 2021). "The diagnostic workflow should begin with a detailed review of clinical data and exclusion of any acquired cases for erythrocytosis; such as compensatory erythrocytosis due to chronic disease or polycythemia vera due to a JAK2 mutation." (PMID 34440324, 2021).